LXN (latexin)
Description:
Hardly reversible, non-competitive, and potent inhibitor of CPA1, CPA2 and CPA4. May play a role in inflammation.
Synonyms: ECI; TCI
Tractability: Small molecule: a structure with a bound ligand is known. PROTAC: ubiquitination databases record sites on it; its protein half-life has been measured.
Gene: Protein-coding gene on chromosome 3 (158,645,822 to 158,672,648, reverse strand). Ensembl gene ENSG00000079257.
Subcellular location: Cytoplasm
Subcellular location (Human Protein Atlas): Cytosol; Nucleoplasm
Gene Ontology:
Molecular function: protein binding; metalloendopeptidase inhibitor activity
Cellular component: cytoplasm
Genetic constraint (gnomAD): Loss-of-function variants: 30 observed, 32.12 expected, observed/expected ratio (o/e) 0.93, 90% interval 0.7 to 1.27. The upper end of that interval is the gene's LOEUF score, 1.27, which puts it in group 5 of 6, group 1 being the genes least tolerant of losing a copy. Missense variants: 227 observed, 265.18 expected, observed/expected ratio (o/e) 0.86, 90% interval 0.77 to 0.96. Synonymous variants: 77 observed, 91.39 expected, observed/expected ratio (o/e) 0.84, 90% interval 0.7 to 1.02.
Homologues: Orthologues: chimpanzee LXN (99% identical), macaque LXN (97% identical), rabbit LXN (88% identical), pig LXN (86% identical), mouse Lxn (85% identical), rat Lxn (84% identical), guinea pig LXN (83% identical), dog LXN (83% identical), zebrafish lxn (37% identical). Paralogues in human: RARRES1 (30% identical).
Diseases named in the same sentence as LXN in open-access papers:
LXN is named in the same sentence as 38 diseases in open-access papers, as found by Europe PMC text mining. Sharing a sentence is not in itself a finding about the gene and the disease. The quoted sentences say what the papers report.
gastric carcinoma (5 papers, 2011 to 2020). A carcinoma that arises from epithelial cells of the stomach. "Evaluation of human gastric cancer samples demonstrated that PRR11 expression was also associated with increased CTHRC1 and decreased LXN expression." (PMID 26252227, 2015). "Among the gastric carcinoma tissues tested, only 14.6% (6/41) were latexin positive, while 75.6% of normal gastric tissues (31/41) were latexin positive (P < 0.05), indicating a correlation of latexin expression with tumorigenesis of gastric cancer." (PMID 21466706, 2011). "To further investigate latexin expression in human tumors, we collected 41 paired gastric carcinomas and adjacent normal tissues and performed immunohistochemical analysis for latexin expression using an anti-latexin monoclonal antibody." (PMID 21466706, 2011). "Immunohistochemical analysis showed significantly reduced latexin expression in gastric carcinomas (6/41, 14.6%) compared to control tissues (31/41, 75.6%) (P < 0.05)." (PMID 21466706, 2011). "To test this possibility, we investigated latexin expression in 41 gastric carcinomas and paired corresponding adjacent normal tissues by immunohistochemical staining of tissue sections." (PMID 21466706, 2011). "Among the gastric carcinoma tissues tested, only 14.6% (6/41) were latexin positive, while 75.6% of normal gastric tissues (31/41) were latexin positive." (PMID 21466706, 2011). "Since downregulated expression of LXN gene was detected in human gastric carcinoma tissues as compared with adjacent normal tissues, the CpG methylation status of the LXN gene in the DNA of paired normal and tumor tissues warrants further investigation." (PMID 21466706, 2011). "Here, we examined latexin expression in human gastric carcinomas and investigated the effect of differential latexin expression on proliferation of gastric cancer cells in vitro and in vivo." (PMID 21466706, 2011). "The cellular and molecular evidences demonstrated the inhibitory effect of latexin in human gastric cancer cell growth and tumorigenicity." (PMID 21466706, 2011). "Evaluation of six gastric cancer cell lines showed latexin expression in only two cell lines, BGC823 and N87, but in all other cell lines tested including MGC803 latexin expression was negative." (PMID 21466706, 2011). "Stable transfection of the LXN gene in human gastric cancer cells MGC803 attenuated cell growth in vitro and in vivo." (PMID 21466706, 2011). "The effects of latexin expression on the tumorigenic potential of gastric cancer cells in vivo were also evaluated." (PMID 21466706, 2011). "In contrast, gastric cancer cells BGC823 transfected with antisense LXN gene expression vector exhibited enhanced capacity for colony formation and tumorigenicity in nude mice." (PMID 21466706, 2011). "The tumor suppressor gene (TSG) latexin (LXN) has been downregulated in a number of human cancers, including lymphoma, gastric carcinoma, and thyroid carcinoma, and the TCGA HNSCC cohort, in congruence with its promoter hypermethylation in Fusobcaterium-high tumor tissues." (PMID 33218162, 2020). "We performed Western blot analysis to explore whether the expression of CTHRC1 and LXN was altered in PRR11-KO SGC-7901 gastric cancer cells." (PMID 26252227, 2015). "Upregulated genes induced by latexin expression in human gastric cancer cells MGC803." (PMID 21466706, 2011). "Additionally, human gastric cancer cells with stably increased or decreased latexin expression were established and used to examine the effect of latexin expression on tumor cell growth and tumorigenesis." (PMID 21466706, 2011). "Downregulated genes induced by latexin expression in human gastric cancer cells MGC803." (PMID 21466706, 2011). "Latexin expression was reduced in human gastric cancers compared with their normal control tissues." (PMID 21466706, 2011).
gastric carcinoma (continued). "Consistent with its tumor suppressor potential, ectopic expression of latexin induced differential expression of several tumor related genes, including Maspin, WFDC1, SLPI, S100P, and PDGFRB, in gastric cancer cells." (PMID 21466706, 2011). "We prepared monoclonal antibody against human latexin and found the reduced latexin expression in human gastric carcinomas as compared with normal control tissues." (PMID 21466706, 2011). "Monoclonal antibody against human latexin was prepared and immunohistochemical analysis was performed to detect latexin expression in 41 paired gastric carcinomas and adjacent normal control tissues." (PMID 21466706, 2011). "Inhibition of latexin expression in both C3 and C7 cells accelerated tumor cell growth in vitro and in nude mice compared with control BGC823 cells, indicating that decreased latexin expression may contribute to tumorigenesis of gastric carcinoma." (PMID 21466706, 2011). "Human gastric cancer cells MGC803 (latexin negative) stably transfected with LXN gene and BGC823 cells (latexin positive) stably transfected with antisense LXN gene were established for anchorage-dependent colony formation assay and tumorigenesis assay in nude mice." (PMID 21466706, 2011).
lymphoma (5 papers, 2011 to 2020). A malignant (clonal) proliferation of B- lymphocytes or T- lymphocytes which involves the lymph nodes, bone marrow and/or extranodal sites. "We found that latexin was down-regulated in a variety of leukemia and lymphoma cell lines as well as in CD34+ cells from the blood and marrow of patients with these malignancies." (PMID 23028717, 2012). "Retrovirus-mediated latexin overexpression in A20 mouse lymphoma cells inhibited their in vitro growth by 16 fold and in vivo tumor volume by 2 fold." (PMID 23028717, 2012). "Elevated latexin expression has also been reported in normal human stem cells compared to the same cell populations from patients with acute myelogenous leukemia (AML) or lymphoma." (PMID 21466706, 2011). "Latexin, also known as endogenous carboxypeptidase inhibitor (CPI), has been found to inhibit mouse stem cell populations and lymphoma cell proliferation, demonstrating its potential role as a tumor suppressor." (PMID 21466706, 2011). "The ectopic expression of latexin in mouse lymphoma cells lacking latexin expression show remarkable suppression of growth in vitro." (PMID 21466706, 2011). "Furthermore, the ectopically expressed latexin in mouse lymphoma cells which are lacking native latexin expression results in remarkable suppression of cell growth." (PMID 25551472, 2014).
breast carcinoma (4 papers, 2014 to 2021). "The complex of piR-932 and PIWIL2 was reported to promote methylation of the promoter region CpG island of the latexin gene, altering latexin expression, and thereby blocking breast cancer metastasis." (PMID 33791297, 2021). "This complex, as a positive regulator promotes Latexin methylation and can be used in order to block the metastasis in breast cancer." (PMID 32211149, 2020). "We next examined the effect of AGBL2-siRNA and latexin on invasion in breast cancer cells using the transwell chamber assay." (PMID 24884516, 2014). "We investigated the expression status of AGBL2 and its inhibitor latexin in breast cancer stem cells and its clinical implications in order to lay a foundation for managing breast cancer." (PMID 24884516, 2014). "In Piwil2 positive breast cancer stem cells, piR-932 could bind with Piwil2 to suppress the expression of Latexin by promoting methylation of the CpG island at its promoter region." (PMID 34295823, 2021). "In view of the negative regulation of cancer stem cells by Latexin, piR-932/Piwil2 could be the potential targets for suppressing the progression of breast cancer." (PMID 34295823, 2021). "Also, in PIWIL2 + breast cancer stem cells, due to the methylation of Latexin promotor region (CpG island), Latexin expression levels are significantly lower than normal." (PMID 32211149, 2020). "We found that the expression level of AGBL2 significantly increased in breast cancer stem cells induced to EMT, as opposed to those that were latexin decreased." (PMID 24884516, 2014).
colorectal cancer (3 papers, 2020 to 2024). A primary or metastatic malignant neoplasm that affects the colon or rectum. "We report that mice loss of LXN significantly promoted the growth of cancer cells in subcutaneous tumor models, and LXN-deficient mice were more susceptibility to develop AOM/DSS-induced colorectal cancer." (PMID 36323670, 2022). "Collectively, these data implicated that LXN deficiency increased PD-L2+ macrophages and decreased T cells infiltration in colorectal cancer tissues, suggesting LXN deficiency enhances pro-tumor immune response in mice." (PMID 36323670, 2022). "Animal studies show that mice loss of LXN promotes tumor growth in subcutaneous tumor model and AOM/DSS-induced colorectal cancer model." (PMID 36323670, 2022). "We show that mice loss of LXN significantly promote the growth of cancer cells in subcutaneous tumor models, and mice are more susceptibility to develop AOM/DSS-induced colorectal cancer in vivo." (PMID 36323670, 2022). "The results showed that mice loss of LXN significantly promoted the growth of cancer cells over the entire assay period in subcutaneous tumor model, no matter loaded with colorectal cancer or lung cancer cells." (PMID 36323670, 2022). "To determine whether PD-L2+ macrophages increased in tumor microenvironment in LXN-deletion mice, we first generated AOM/DSS-induced colorectal cancer model in WT and LXN−/− mice." (PMID 36323670, 2022). "In this study, we did not detect the effect of LXN on the infiltration of immune cells during the development of DSS colitis, nor did we further observe whether the LXN deficiency affects the occurrence of colorectal cancer." (PMID 32555320, 2020). "LXN directly targets and inhibits JAK1, which attenuates the activity of STAT3, consistent with our previous reports on colorectal inflammation and colorectal cancer in LXN knockout mice." (PMID 39424784, 2024).
melanoma (3 papers, 2015 to 2025). A malignant, usually aggressive tumor composed of atypical, neoplastic melanocytes. "IGFBP7 and Latexin (highest up- and downregulated expression in microarray analysis) were found to be associated with longer and shorter survival, respectively, of melanoma patients." (PMID 30089785, 2018). "High expression of CEACAM1 in the melanoma samples correlated with high LXN expression (φ = 0.37, p < 0.001) and also CEACAM1 staining in a certain area of an individual melanoma often correlated with LXN staining intensity in the same area (serial sections)." (PMID 30089785, 2018). "It has also reported that LXN has tumor suppressive properties in malignant melanoma and hepatocellular carcinoma." (PMID 26252227, 2015). "The epigenetic modulation of αVβ3 integrin might be involved in melanoma progression, furthermore, latexin (a negative regulator of HSCs) is downregulated in one-out-of-two melanomas, with its promoter region hypermethylated in melanomas and other cancers." (PMID 40427015, 2025). "According to the results from the xenograft experiment, we hypothesized that melanoma cells with high LXN expression also have a higher metastatic potential than LXN low cells." (PMID 30089785, 2018). "In the study cited above, most melanoma samples showed only low immunohistochemical LXN staining." (PMID 30089785, 2018). "LXN expression could be investigated by immunohistochemistry in melanoma from 105 patients of the same cohort from which the results for CEACAM1 expression were obtained." (PMID 30089785, 2018). "Additionally, melanoma cells with forced LXN expression showed reduced proliferation." (PMID 30089785, 2018). "High LXN expression in the melanoma specimens correlated with shortened patient survival (age-adjusted HR 4.0, 95%-CI [1.8;9.1]; p = 0.001), with a 5-year survival of 88.9% (95%-CI [75.3;95.2]) in the LXN low patients in comparison with 55.0% (95%-CI [41.6;66.5]) for the LXN high patients." (PMID 30089785, 2018). "The markers CEACAM1, FOSL1, IGFBP7, LXN and cytoplasmic/nuclear TWIST were used as predictors in a multivariate Cox model (adjusted for age) for the prognosis of the melanoma patients’ survival." (PMID 30089785, 2018). "In the melanoma samples, high expression of CEACAM1 did not correlate with low IGFBP7 expression and low IGFBP7 expression did not correlate with high LXN expression (φ = −0.01, p = 0.911 and φ = 0.03, p = 0.781, respectively)." (PMID 30089785, 2018).
atherosclerosis (2 papers, 2021 to 2024). A disease characterized by the build-up of fatty material and calcium deposition in the arterial wall resulting in partial or complete occlusion of the arterial lumen. "This study shows that LXN deficiency markedly improves atherosclerosis through the inhibition of foam cell formation." (PMID 39424784, 2024). "We first demonstrated that LXN expression is increased and colocalizes with macrophages in both human and murine atherosclerotic lesions, and that LXN deficiency decreases atherosclerosis in ApoE-/- mice." (PMID 39424784, 2024). "We found that LXN deficiency significantly improves vascular permeability, vasodilation and atherosclerosis in mice." (PMID 34085389, 2021). "Animal models show that LXN deficiency significantly improves vascular permeability, vasodilation and atherosclerosis in mice." (PMID 34085389, 2021). "Importantly, adeno-associated virus mediated gene therapy to reduce LXN in ApoE-/- mice revealed that LXN deficiency improves atherosclerotic plaque formation in the mouse atherosclerosis model." (PMID 39424784, 2024). "We further evaluated the vascular protective role of LXN deficiency in atherosclerosis." (PMID 34085389, 2021). "Importantly, we show that LXN deficiency significantly improves vascular permeability, vasodilation and atherosclerosis in mice, which indicated LXN deficiency has a protective effect on vascular homeostasis, and provides new targets for the treatment of vascular diseases." (PMID 34085389, 2021). "Both genetic ablation of LXN and BMT with LXN-deficient hematopoietic cells improved atherosclerosis in ApoE-/- mice." (PMID 39424784, 2024). "Taken together, these findings confirm that suppressing LXN by genetic disruption can effectively improve atherosclerosis in ApoE-/- mice." (PMID 39424784, 2024). "In this study, we report a new physiological function of LXN in atherosclerosis through mechanisms involving modulation of the macrophage anti-inflammatory phenotype and cholesterol efflux." (PMID 39424784, 2024). "Our findings underscore the function of LXN as a critical regulator of atherosclerosis, and identify macrophage LXN as a potential novel therapeutic target against atherosclerosis." (PMID 39424784, 2024). "LXN knockout and LXN/ApoE double-knockout mice were generated to evaluate the functions of LXN in atherosclerosis." (PMID 39424784, 2024). "Increased LXN expression substantially exacerbated atherosclerosis, while LXN disruption markedly reversed atherosclerosis, including decreased macrophage infiltration and reduced macrophage-rich fatty streaks." (PMID 39424784, 2024). "Our findings provide new clues for the physiological role of macrophage LXN in the regulation of atherosclerosis and identify macrophage LXN as a target to prevent cardiovascular disease." (PMID 39424784, 2024). "We also verified the critical function of macrophage-derived LXN in atherosclerosis by BMT experiments." (PMID 39424784, 2024). "Collectively, our data reveal that global LXN deletion protects ApoE-/- mice against atherosclerosis." (PMID 39424784, 2024). "Much is known about macrophages in atherosclerosis, the role of macrophage LXN in atherosclerosis has remained elusive." (PMID 39424784, 2024). "To begin to understand the function of LXN in atherosclerosis, we examined its expression in atherosclerotic lesions." (PMID 39424784, 2024). "In animal models, we demonstrate that LXN deficiency inhibits VEGF and TNF‐α‐induced vascular permeability, as well as significantly improves vasodilation and atherosclerosis in mice fed with high‐fat diet." (PMID 34085389, 2021). "Next, we investigated the function of LXN in atherosclerosis." (PMID 39424784, 2024). "BMT demonstrate that deletion of LXN in bone marrow protects ApoE-/- mice against atherosclerosis." (PMID 39424784, 2024).